APOE (apolipoprotein E)
Diseases named in the same sentence as APOE in open-access papers (continued):
Sharing a sentence is not in itself a finding about the gene and the disease.
type 2 diabetes (continued). "In contrast, apoC3 abrogates the benefit of apoE on reverse cholesterol transport, which may account for the association of HDL that contains apoC3 with type 2 diabetes and other diseases." (PMID 38438344, 2024). "Not of statistical significance, APOE ε2 showed a trend to protect against type 2 diabetes (OR = 0.342; p = 0.093), in contrast BIN1 rs744373 risk-allele carriers were more likely to exhibit the disease (OR = 1.491; p = 0.099)." (PMID 39081475, 2022). "We hypothesized that the associations between subcortical structural alterations and AD pathology in type 2 diabetes patients can be disentangled by calculating the direct and indirect effects of type 2 diabetes, age and ApoE-ε4 on each process." (PMID 35173604, 2022). "Apolipoprotein E modulates the relationship between AD and Type 2 diabetes." (PMID 35336756, 2022). "Therefore, to reduce potential bias, it is necessary to take age and ApoE-ε4 into account when analyzing the influence of type 2 diabetes on cognition in future research." (PMID 35173604, 2022). "People with both APOE ε4 and type 2 diabetes had a significantly higher risk of AD than non-carriers." (PMID 30866553, 2019). "No SNP or haplotype association was detected between the APOE promoter and the risk of type 2 diabetes." (PMID 22028770, 2011). "At physiological level, there is a lack of evidence of association between the three APOE promoter SNPs −491A/T (rs449647), −219G/T (rs405509), and +113G/C (rs440446) and the risk of type 2 diabetes." (PMID 22028770, 2011). "Again, we did not detect an association between APOE promoter SNPs and the duration of type 2 diabetes (data not shown)." (PMID 22028770, 2011). "A recent meta-analysis of genome-wide linkage studies of quantitative lipid traits in families ascertained for type 2 diabetes with diverse ethnic backgrounds identified one of the linkage region for lipid traits on chromosome 19q13.13-13.43 which included the APOE gene locus (19q13.2)." (PMID 22028770, 2011). "In addition, the association of type 2 diabetes with cognitive dysfunction was not modified by APOE ε4 carriership." (PMID 24367577, 2013). "First, we evaluated major subcortical structural alterations in patients with type 2 diabetes, after conducting propensity score matching (PSM) to reduce the potential biases from age, sex, and ApoE-ε4." (PMID 35173604, 2022). "In the present study apoE, apoC-II and apoC-III levels were higher in those study participants who later developed incident type 2 diabetes, when adjusted for age, sex, and anthropometric measures." (PMID 30599058, 2019). "Aggregated Aβ, hyperphosphorylated tau, ubiquitin, apolipoprotein E, apolipoprotein(a), IB1/JIP-1 and JNK1 are immuno-expressed in the affected Langerhans islets in patients with type 2 diabetes and Aβ is colocalized with amylin." (PMID 26961231, 2016). "Trehalose, a non-reducing disaccharide, and metformin, the type II diabetes drug, have both been found to enhance autophagy and were investigated for their potential to modulate visual dysfunction in aging WT and APOE mice." (PMID 35196199, 2022). "Among them, age and ApoE-ε4 strongly contributed to AD pathology, while type 2 diabetes neither directly nor indirectly affected AD biomarkers." (PMID 35173604, 2022). "Nondiabetic ApoE−/− mice, streptozotocin-induced diabetic ApoE−/− mice, and db/db (a mouse model of type 2 diabetes) mice were administered GIP or saline (vehicle) through osmotic mini-pumps for 4 weeks." (PMID 35205155, 2022). "Patients with type 2 diabetes also have reduced ApoE content in large HDL particles, which may have an atherogenic effect, since large, ApoE-rich HDL usually prevents LDL binding to proteoglycans in the vessel wall." (PMID 25725623, 2015). "However, the relationship between APOE polymorphisms and type 2 diabetes (T2DM) with or without CVD remains unclear." (PMID 31521122, 2019).
type 2 diabetes (continued). "Empagliflozin for 8 weeks decreased body weight and particularly adipose tissue in APOE(−/−) mice, while did not affect the weight of ZDF rats (type 2 diabetes model)." (PMID 30049285, 2018).
Parkinson disease (148 papers, 2009 to 2026). A progressive degenerative disorder of the central nervous system characterized by loss of dopamine producing neurons in the substantia nigra and the presence of Lewy bodies in the substantia nigra and locus coeruleus. "The ApoE ε4 has been associated with various neurodegenerative diseases, including AD, Parkinson’s disease, ischemic stroke, and multiple sclerosis." (PMID 40349252, 2025). "It is also recognized that the LBD risk variables that have been established also carry the risk for AD (APOE) or Parkinson's Disease (PD) (GBA, SNCA)." (PMID 38607741, 2024). "Genome‐wide association studies have identified several genetic susceptibility loci for Parkinson's disease (PD), including the apolipoprotein E (APOE) ε4 allele." (PMID 38026513, 2023). "It was reported that the haplotypes of both ApoE and Tau have been linked to AD and other neurodegenerative diseases including in frontotemporal dementia, Huntington’s disease, and Parkinson’s disease." (PMID 30909239, 2019). "APOE gene ε2/ε3/ε4 polymorphism has been associated with several neurodegenerative diseases such as Alzheimer's and Parkinson's diseases." (PMID 24885013, 2014). "Since APOE ε2 has previously been associated with PD, it is reasonable to suggest that APOE ε2 is linked to parkinsonism in SCA3." (PMID 41210483, 2025). "However, there is significant evidence to suggest an association between Parkinson’s disease and the APOE genotype, such that PD is highly associated with APOE ε2/ε4 (p < 0.0004), and ε3/ε3 (p < 0.0011)." (PMID 40018689, 2025). "It is intriguing to note that while there is extensive molecular evidence linking APOE protein to AD-specific pathways, associations have been found between mutations in the APOE gene and the risk of various other neuropsychiatric disorders such as multiple sclerosis and Parkinson's disease." (PMID 39736972, 2024). "Furthermore, apoE has been implicated in a number of Aβ-independent pathogenic mechanisms that cause Parkinson’s disease, primary tauopathies, and amyotrophic lateral sclerosis, among other disorders." (PMID 35768831, 2022). "APOD and APOE have also been implicated in Parkinson’s disease." (PMID 33478506, 2021). "In addition, ApoE variants are not only involved in AD, but several studies also report an association between ApoE e4 and Parkinson’s Disease (PD)." (PMID 33804213, 2021). "Phenotypic associations of tau and ApoE in Parkinson's disease." (PMID 21034472, 2010). "Notably, βA42 immunoreactivity was observed in a significant proportion of subjects younger than 25 years old, particularly in those carrying the APOE 4 allele, while alpha-synuclein, an aggregate related to Parkinson’s disease (PD), was detected in nearly a quarter of this age group." (PMID 39000036, 2024). "Of note, whether APOE ε4 increases the risk of vascular dementia, frontotemporal dementia, dementia with Lewy bodies, and Parkinson’s disease is unclear." (PMID 32036490, 2020). "Additionally, ibuprofen can regulate the activity of the protein apolipoprotein E that associated with the neurodegenerative processes in mammalian brain, including development of Alzheimer's and Parkinson's diseases, through the COX-2 inhibition and PPAR-γ activation." (PMID 28066251, 2016). "APOE gene ε2/ε3/ε4 polymorphism has been associated with a number of neurodegenerative diseases such as Alzheimer's and Parkinson's diseases, raising the possibility that this polymorphism might predispose to neurodegeneration of the retinal ganglion cells and the optic nerve axons in glaucoma." (PMID 24885013, 2014). "Eight loci-PRKN, SNCA, GBA1, LRRK2, APOE, MTHFR, SYT11, and NR4A2-emerged as recurrently associated with Parkinson's disease." (PMID 41798285, 2026). "A further case report of two SCA3 patients presenting parkinsonism identified a common ApoE genotype, namely APOE ε2/ε3." (PMID 41210483, 2025).
Parkinson disease (continued). "For example, PMID﻿30,409,187 is focusing on Parkinson’s Disease and APOE is only mentioned once in the “Methods” section." (PMID 38632621, 2024). "In Parkinson’s disease, APOE-ε4, one of the phenotypes of APOE, is well known to promote neurodegenerative disease." (PMID 38600296, 2024). "By combining the APOE ɛ4 allele carriage status, NCI-MSA patients had significantly younger age of onset of the disease, of parkinsonism and dysautonomia compared to other cognitive subgroups (p = 0.05, p = 0.043 and p = 0.05 respectively)." (PMID 36508411, 2022). "Excluding the APOE locus from the overlapping genes also showed an enrichment of AD-related phenotypes, but also of other diseases, such as sarcoidosis and Parkinson’s disease." (PMID 35589863, 2022). "Another former study reported decreases of apolipoprotein AII and apolipoprotein E in Parkinson’s disease." (PMID 32714143, 2020). "CAF interacts with specific genetic variants such as MAPT, SLC2A13, LRRK2, ApoE, NOS2A, GRIN2A, CYP1A2, and ADORA2A, which may influence the risk of developing Parkinson’s Disease (PD)." (PMID 40650030, 2025). "Thus, the apoE4 effects on Parkinson’s disease are also due to its gain-of-function property instead of a dysfunctional apoE protein." (PMID 36077289, 2022). "However, they may also include neuroplasticity consequences of COMT, APOE and MAPT functional polymorphisms in the context of Parkinson’s disease pathogenesis, or developmental effects even if these diminish with older age (e.g. for COMT)." (PMID 25080285, 2014). "In the NHP CSF, 983 proteins were identified by at least two unique peptides, including proteins with key roles in neurological diseases, such as APP, TREM2 and ApoE in AD, DJ-1/PARK7 in Parkinson’s disease and the prion protein in prion diseases." (PMID 36810097, 2023). "Confirming these preliminary observations, ANCOVA analyses (adjusted for age and APOE genotype) indicated that the DAT SBr in these regions were significantly different across the three groups (p < 0.001), with subjects with Parkinson’s disease demonstrating highly reduced DAT SBr in the regions." (PMID 40018689, 2025). "Interestingly, subject IV25, but not the index multiple system atrophy case or the other family member with Parkinson’s disease from generation III, was a heterozygous ApoE ɛ4 carrier." (PMID 35855480, 2022). "The strongest evidence for the role of APOE-ε4 isoforms in non-AD neurodegenerative diseases can be mapped to dementia with Lewy bodies (DLB) as in the case of Parkinson's disease (PD)." (PMID 35071357, 2021).
tauopathy (143 papers, 2011 to 2025). Neurodegenerative disorders involving deposition of abnormal tau protein isoforms (tau proteins) in neurons and glial cells in the brain. "The review also explores protective effects of ApoE mutations against AD and ApoE4-induced tauopathy, neurodegeneration, and neuroinflammation." (PMID 39944166, 2025). "Particularly intriguing is the APOE R136S Christchurch mutation, which reduces heparan sulfate binding and is associated with resilience to tauopathy." (PMID 40883746, 2025). "Current understanding of the AD pathophysiology implicates the aggregation of amyloid beta (Aβ) as causative to neurodegeneration, with tauopathies, apolipoprotein E and neuroinflammation considered as other major culprits." (PMID 38242873, 2024). "SCFAs can modulate Aβ plaques in the brain, astrocytic gene expression, expression of tight junction proteins, directly act on afferent vagal fibers, and induce ApoE-associated Tauopathy." (PMID 37162940, 2023). "Taken together, these findings offer a better understanding of the relationship between the APOE genotype and sleep in Aβ and Aβ-linked tauopathy and suggest unique early therapeutic strategies to treat AD." (PMID 37279069, 2023). "Our findings indicate that APOE genotype plays a regulatory role in tauopathy, though the exact pathogenic mechanism remains elusive." (PMID 37337279, 2023). "The MAPT H1 haplotype, for example, has been found to be associated with increased risk in developing PSP, CBD, and AD (only in non-ApoE-4 carriers), suggesting a common genetic link between tauopathies that contain 4-repeat scripts." (PMID 36597124, 2023). "For example, in participants with AD, APOE ε4 allele status influences CSF measures of tauopathy, itself associated with night-time behaviour disturbance." (PMID 35354468, 2022). "The connection of ɛ2 to tau is supported by evidence that ε2 is associated with increased tau in mice expressing APOE ε2/ε2 and with increased tau pathology in the brains of human tauopathy cases." (PMID 34480088, 2021). "In summary, our current study provides new insights into the variants in the top 30 non-APOE AD risk genes associated with transcript expression levels and involved in the pathological processes of brain amyloidosis, tauopathy, and neurodegeneration." (PMID 33419465, 2021). "In our analysis of pathologies that frequently co-occur with the accumulation of β-amyloid and tauopathy, we replicated the positive association between Lewy body burden and the APOE ε4 allele." (PMID 33376986, 2020). "We found that CSF sTREM2 associated with age-related neuroinflammation and tauopathy irrespectively of amyloid β, APOE ε4 status or gender." (PMID 32985583, 2020). "It would also be particularly informative to further investigate different APOE alleles in various primary tauopathies and tauopathy mouse models at different disease stages." (PMID 31277708, 2019). "The combined results of our studies demonstrate that APOE ε2/ε2 is related with increased risk and APOE ε2 with severity of tau pathology in a relatively common primary tauopathy." (PMID 30348994, 2018). "ApoE-deficient mice (ApoE−/−) represent a well-established mouse model of tauopathy with memory deficits." (PMID 27902456, 2016). "ApoE−/− mice are known for their significant loss of synapses with increasing age and further are also described as model of tauopathy." (PMID 27902456, 2016). "Similarly, animal literature demonstrated that a human APOE ɛ4 knock‐in exacerbates tauopathy‐associated neurodegeneration." (PMID 41451854, 2025). "Furthermore, the APOE ε2 allele was associated with increased tau pathology in the brains of human progressive supranuclear palsy, a primary tauopathy." (PMID 41384508, 2025). "For several tauopathies, including AD, the APOE genotype is the major genetic risk factor." (PMID 39524360, 2024).
tauopathy (continued). "Our study sheds light on the intricate regulatory roles of ApoE isoforms in modulating the Wnt signaling pathway, providing insights into potential mechanisms underlying the resistance to tauopathy observed in Patient α, the ApoE3Ch-carrying individual with the PSEN1 E280A mutation." (PMID 38571814, 2024). "Indeed, it has now been realized that, in addition to Aβ amyloidogenesis, tauopathies, apolipoprotein E, and neuroimmune activation are all causative to neurodegeneration in AD13." (PMID 38242873, 2024). "AGD is a poorly understood four‐repeat (4R) tauopathy occurring in old age and is known to associate strongly with the APOE ε2 allele, and we therefore postulate that the linkage between PART and AGD in our study could be mediated by the APOE ε2 allele." (PMID 34927275, 2022). "Thus, which specific APOE allele directly underlies the induction and subsequent transmission of tauopathy is uncertain." (PMID 35440098, 2022). "To investigate whether APOE alleles influence the prionoid induction and spread of tauopathy, we injected human K18-tau aggregates unilaterally into the left hippocampus of 2.5 month old PS/E2H, PS/E3H and PS/E4H mice and analyzed ptau burden after 5 months." (PMID 35440098, 2022). "Of the 3 APOE isoforms, APOE ε4 is the strongest and most common genetic risk factor for late-onset AD as compared to the most common APOE isoform, APOE ε3, while the third isoform, APOE ε2, may increase risk for primary tauopathies." (PMID 33815065, 2021). "We comprehensively evaluate the roles of the variants in top 30 non-APOE AD risk genes, based on whether these variants were associated with altered mRNA transcript levels, as well as brain amyloidosis, tauopathy, and neurodegeneration." (PMID 33419465, 2021). "Interestingly, ApoE4 aggravates neurodegeneration in a mouse model of tauopathy independently of Aβ and renders neurons more vulnerable to degeneration, whereas the deficiency of ApoE is neuroprotective." (PMID 31130847, 2019). "Together, our results support a pathogenic risk of APOE ε2 gene allele with primary tauopathies." (PMID 30348994, 2018). "Recent studies show that APOE-ε4 may associate with cerebrospinal fluid (CSF) levels of tau and p-tau, as well as possible associations and/or interactions between APOE and tauopathies in the setting of β-amyloid deposition." (PMID 30223506, 2018). "Finally, we identify an association between the APOE ε2/ε2 genotype and risk of tauopathies using two series of pathologically-confirmed cases of PSP and corticobasal degeneration." (PMID 30348994, 2018). "The APOE E4 allele and the pathogenesis of AD are connected by these findings, implying that APOE E4, which is generated from astrocytes, could be a factor in regulating tauopathies." (PMID 37638434, 2023). "Additionally, the discovery of microtubule-associated protein tau (MAPT) gene mutations and the strongest genetic risk factor of tauopathies—an increase in the presence of the ε2 allele of apolipoprotein E (ApoE)—provide important clues to understanding tau pathology progression." (PMID 33672982, 2021). "ApoE is a major genetic risk factor for sporadic AD, where, in the brain, apoE is produced by astrocytes, microglia, pericytes and stressed neurons and contributes to AD pathogenesis by modulating multiple pathways, including but not limited to Aβ metabolism, tauopathy, and neuroinflammation." (PMID 32213187, 2020). "Our data together suggest APOE ε2 status may influence the risk and progression of tauopathy." (PMID 30348994, 2018). "These efforts have resulted in identifying multiple mechanisms by which APOE influences AD‐related pathologies, including amyloid beta (Aβ) accumulation, tauopathy, neuroinflammation, and synaptic impairment." (PMID 41384508, 2025).